SPOP (speckle type BTB/POZ protein)
Diseases named in the same sentence as SPOP in open-access papers (continued):
Sharing a sentence is not in itself a finding about the gene and the disease.
prostate carcinoma (continued). "Overexpression of SPOP in LNCaP prostate cancer cells resulted in a marked reduction of the endogenous level of AR protein in a dose-dependent manner." (PMID 24508459, 2014). "Of the 23 newly identified susceptibility loci for prostate cancer, rs11650494 is located at chromosome 17q21, a gene-dense locus that contains several prostate cancer candidate genes such as HOXB13 and SPOP." (PMID 23852643, 2013). "Articles that did not align with the predefined inclusion criteria, such as those lacking relevance to SPOP mutations in prostate cancer or those with insufficient data, were excluded." (PMID 40432836, 2025). "In the context of prostate cancer, SPOP targets the AR for ubiquitylation and degradation." (PMID 40432836, 2025). "This unique molecular profile contributes to the heterogeneity of SPOP-mutant prostate cancers." (PMID 40432836, 2025). "SPOP mutations can impact the response to ADT, a common treatment for advanced prostate cancer." (PMID 40432836, 2025). "Articles that did not provide pertinent information on SPOP mutations in prostate cancer, did not contribute to disease characterization, or did not address therapeutic implications were excluded." (PMID 40432836, 2025). "SPOP mutations also promote p62/SQSTM1-dependent autophagy and NRF2 activation in prostate cancer." (PMID 39851497, 2025). "Thus, the SPOP E3 ligase acts as a novel negative regulator of Cdc20, which in turn influences cell viability and apoptosis in prostate cancer." (PMID 40771930, 2025). "SPOP (spotted POZ protein), a substrate-interacting junction protein within the Cullin 3-based E3 ubiquitin ligase complex, exhibits a mutation rate of 10%–15% and is a critical molecular feature of prostate cancer (PCa)." (PMID 40771930, 2025). "Additionally, there is evidence that SPOP specifically interacts with proteins through its N-terminal MATH structural domain in the context of prostate cancer." (PMID 40771930, 2025). "Notably, SPOP-mutant prostate cancers are mutually exclusive with TMPRSS2-ERG fusions and enriched for Wnt pathway alterations." (PMID 40432836, 2025). "In the context of hypoxia-driven pathways, EGLN2 (egl-9 family hypoxia-inducible factor 2), a key regulator of cellular adaptation to low oxygen, shows elevated expression in prostate cancer, and its ubiquitination by the tumor suppressor SPOP constrains cancer cell growth." (PMID 41468516, 2025). "Moreover, the ELK3 protein half-life was notably extended in SPOP knockdown Du145 prostate cancer cells." (PMID 38632244, 2024). "The co-occurrence of CHD1 deletion and SPOP mutation in ERG fusion–negative prostate cancer has been described previously, but progression modeling reveals these as early, codriving events." (PMID 39347576, 2024). "CDC20 itself is a target for ubiquitination by the E3 ligase SPOP, which is commonly mutated and non-functional in prostate cancers, providing an explanation for elevated CDC20 levels." (PMID 37509260, 2023). "Notably, a substantial proportion of prostate cancers, up to 74%, can be attributed to fusions found in ETS-family genes (ERG, ETV1, ETV4, and FLI1) or mutations in genes such as SPOP, FOXA1, or IDH1." (PMID 38067216, 2023). "Besides the phosphorylation, the speckle type BTB/POZ protein (SPOP)-mediated BRD4 ubiquitination regulates BRD4 degradation in prostate cancer." (PMID 37737256, 2023). "In addition, it has been reported that the activation of CDK1/SPOP signaling by the ATR inhibition enhanced the cytotoxicity of ICIs in prostate cancer." (PMID 37528490, 2023).
prostate carcinoma (continued). "DNA damage caused by genotoxic agents, such as docetaxel, CPT and IR, may lead to the degradation of normal ERG and TMPRSS2–ERG proteins in a SPOP-independent manner, suppressing prostate cancer." (PMID 35954292, 2022). "It has been reported that SPOP is the most common mutant gene in prostate cancer." (PMID 35402244, 2022). "Tumor-suppressive effects of SPOP in prostate cancer, where it acts as a negative regulator of BET protein stability, and also provides a molecular mechanism for resistance to BET inhibitors in individuals with prostate cancer carrying SPOP mutations." (PMID 36171897, 2022). "SPOP was found to be the most common missense mutated gene in human prostate cancers and has been shown to be associated with the pathogenesis of primary prostate tumours, but SPOP mutations in RCC tumours have not yet been reported." (PMID 36474188, 2022). "Indeed, it has been shown that cells expressing prostate cancer-derived SPOP mutants are resistant to BET inhibitor due to elevated expression of BET family proteins BRD2, BRD3, and BRD432,33." (PMID 34599168, 2021). "Another study also revealed that down-regulated SPOP occurred early in prostate tumorigenesis, suggesting that SPOP was an oncogene that could be a predictive marker for prostate cancer." (PMID 34838022, 2021). "In the same way, prostate tumoroids have revealed that prostate cancer-associated SPOP mutations confer resistance to BET inhibitors through the stabilization of BRD4, enabling a deeper understanding of how prostate cancers of certain patients respond to treatment according to their genetic lesions." (PMID 34327198, 2021). "Conversely, forced expression of ΔERG significantly reduced the growth of SPOP-Y83C mutant LuCaP-147 patient-derived xenograft (PDX) cancer cells in vivo and in culture 17, adding orthogonal support for a synthetic sick relationship between mutant SPOP and ΔERG in advanced prostate cancer." (PMID 33531470, 2021). "To mimic the pathophysiological conditions in patients, we introduced the mutated allele of SPOP into prostate cancer cell lines that do not contain endogenous mutated SPOP." (PMID 34599168, 2021). "Our finding that SPOP mutation triggers replication catastrophe, massive DNA breaks, and cell death upon ATR inhibition highlights that prostate cancers harboring SPOP mutations may be susceptible to treatment with ATR inhibitors." (PMID 34599168, 2021). "Based on genomic profiles, prostate cancer can be divided into seven molecular subtypes which bear distinct oncogenic drivers including fusions with ETS family members (ERG, ETV1, ETV4, and FLI1) and mutations in SPOP, FOXA1, and IDH1." (PMID 33273988, 2020). "Expression of prostate cancer-associated SPOP mutants also caused the accumulation of DSBs in prostate cancer cells in the absence of exogenous DNA damage stresses." (PMID 33023230, 2020). "An earlier study of a cohort of 333 primary prostate carcinomas showed that 74% of these tumors fell into one of seven subtypes of a molecular taxonomy defined by specific gene fusions (ERG, ETV1/4 and FLI1) or mutations (SPOP, FOXA1 and IDH1)." (PMID 33058520, 2020). "In prostate cancer, tumor suppressor SPOP interacts with Nanog and promotes Nanog poly-ubiquitination and subsequent degradation, but Pin1 functions as an upstream Nanog regulator and impairs its recognition by SPOP, stabilizing Nanog to promote the cancer stem cell traits and tumor progression." (PMID 32296699, 2020). "Therefore, SPOP mutations fail to mediate CHOP degradation, indicating a CHOP involvement in the progression of prostate cancer associated with SPOP mutations." (PMID 32560326, 2020). "A study of a cohort of 333 primary prostate carcinomas showed that 74% of these tumors fell into one of seven subtypes of a molecular taxonomy defined by specific gene fusions (ERG,ETV1/4 and FLI1) or mutations (SPOP,FOXA1 and IDH1)." (PMID 33058520, 2020).
prostate carcinoma (continued). "For example, SPOP functions as a tumor suppressor in prostate cancers, and may act as an oncogene in breast cancers and ccRCC." (PMID 33023230, 2020). "This hypothesis remains to be tested but it grants further investigation of ZBTB38 as a molecular driver of prostate cancer progression, in relation to SPOP/SPOPL functions." (PMID 32365491, 2020). "For example, the ubiquitin ligase SPOP (Speckle-type POZ protein) may modulate DSB in prostate cancer." (PMID 35692625, 2020). "Another small molecule inhibitor of PIN1, PiB, inhibited both SPOP-mediated NANOG degradation and stemness-associated spheroid formation in prostate cancer cells; the application of PIN1 inhibitors against prostate cancer with wild-type SPOP was suggested by the researchers." (PMID 32268506, 2020). "Therefore, according to our findings, it is unlikely that in Jordanian population SPOP and PIK3CA hotspot mutations contribute to prostate cancer or they do but in a much lower percentage." (PMID 33247697, 2020). "SPOP (speckle-type POZ protein) was identified as one of the most frequently affected genes through somatic point mutations in prostate cancer, suggesting SPOP is potentially a key driver for prostate cancer development and progression." (PMID 32560326, 2020). "In this study, we demonstrate that SG assembly is elevated in SPOP-mutant prostate cancer cells." (PMID 31771591, 2019). "TRIM24 becomes stabilized in prostate cancer with SPOP mutations, through mechanisms involving TRIM28, upregulated in aggressive prostate cancer and associated with elevated TRIM24 levels: TRIM28 interacts with TRIM24 to prevent its ubiquitination and degradation by SPOP." (PMID 31366128, 2019). "Hence, SPOP mutant prostate cancers are resistant to BET inhibitor owing to having more stabilized BET proteins than SPOP-wt cancers." (PMID 31311566, 2019). "Wild-type SPOP, but not the prostate cancer-associated SPOP mutants, suppresses SG assembly by promoting ubiquitination and degradation of Caprin1, a SG nucleating oncoprotein previously found overexpressed in various cancers." (PMID 31771591, 2019). "Extensive genomic studies identified SPOP as a tumor-suppressor in prostate cancer (PCa) tissues." (PMID 30237511, 2019). "To determine the biological importance of SPOP regulation of Caprin1-mediated SG assembly in prostate cancer, we first investigated whether Caprin1 expression is important for maintaining the neoplastic phenotypes of prostate cancer cells." (PMID 31771591, 2019). "Analysis of a large number (>8000) prostate cancer patients allowed defining the clinicopathologic features of SPOP-mutant tumors: lower frequency of positive margins, extra prostatic extension, and seminal vesicle invasion at prostatectomy; higher pretreatment serum PSA levels." (PMID 31366128, 2019). "Taken together, these results suggested that the SPOP-Caprin1 regulatory axis might be critical for cell survival under environmental stress in prostate cancer cells." (PMID 31771591, 2019). "Furthermore, we found SPOP selectively regulates the substrates’ stability and signaling pathways in prostate cancer and CCRC cell lines, suggesting that complicated mechanisms exist for SPOP to regulate substrate specificity." (PMID 30237511, 2019). "Frequent mutations in SPOP occur in domains that interfere with E3 substrate binding and may affect SPOP's ability to degrade androgen receptors that contribute to cancer development in prostate cancer and progesterone receptors in breast cancer cells." (PMID 29594129, 2018). "Nearly 50% of prostate cancers harbor gene fusions that lead to overexpression of the transcription factor ERG, while a mutually exclusive 10% of prostate cancers harbor recurrent mutations in the gene encoding the E3 ubiquitin ligase SPOP." (PMID 29202479, 2018). "SPOP (Speckle-type POZ Protein) is one of the most frequently mutated genes in primary prostate cancer, suggesting that SPOP may be a potential driver of prostate cancer." (PMID 29996942, 2018).
prostate carcinoma (continued). "Genomically, 70% of prostate cancers harbor PTEN alterations and 10% harbor SPOP mutations." (PMID 29572264, 2018). "Moreover, resistance to JQ1 itself has also been demonstrated through SPOP mutation, which contributes to resistance to BET inhibitors through BRD4 stabilization in prostate cancer." (PMID 29796168, 2018). "Here, we test this hypothesis using human prostate cancer specimens and genetically engineered mouse models of SPOP-mutant prostate cancer." (PMID 29202479, 2018). "Speckle-type POZ protein (SPOP) is an E3 ubiquitin ligase adaptor protein that functions as a potential tumor suppressor, and SPOP mutations have been identified in ~10% of human prostate cancers." (PMID 28810879, 2017). "Overexpression of wild-type SPOP, but not the prostate cancer-associated mutants of SPOP, reduced the protein amounts of GFP-INF2 in ER fractions." (PMID 28448495, 2017). "Interestingly, the E3 ubiquitin ligase SPOP is a frequently inactivated tumor suppressor in prostate cancer." (PMID 28486411, 2017). "Moreover, INF2 is important for SPOP inactivation-induced prostate cancer cell migration and invasion." (PMID 28448495, 2017). "Taken together, our data suggest that wild-type SPOP, but not prostate cancer-associated mutants, can suppress INF2-mediated mitochondrial fission." (PMID 28448495, 2017). "Taken together, our data suggests that wild-type SPOP, but not prostate cancer-associated mutants, can promote INF2 disassociation from ER." (PMID 28448495, 2017). "Fourteen DNA repair genes and 15 hormone-regulated genes contributed to the high trigger score for the 7p14.3 variant, of which DAZAP2, DDX18, SET, and XRCC5 were also significantly deregulated in SPOP mutant as compared to SPOP wild-type human prostate carcinoma cases." (PMID 28663546, 2017). "Two recent studies have suggested that dysregulation of the SPOP ubiquitin ligase complex in ERG-overexpressing prostate cancer cells reduces ERG ubiquitination, and that stabilized ERG was responsible for the enhanced migration and invasion activities of cells carrying SPOP mutations." (PMID 27208692, 2016). "To test this hypothesis in human prostate cancers, we performed unsupervised hierarchical clustering of transcriptional data from 11 SPOP mutant and 53 SPOP wild-type tumors, based on the transcriptional signature of BRCA1 inactivation (MSigDB: M2748)." (PMID 26374986, 2015). "Strikingly, SPOP-F133V-expressing prostate cells showed delayed clearance of 53BP1 from sites of DSB; similar effects were seen with another SPOP mutation (F102C) commonly observed in prostate cancer." (PMID 26374986, 2015). "Importantly, after DSB induction, this loss of function leads to an increased sensitivity of mutant SPOP prostate cancer cells to PARP inhibition." (PMID 26374986, 2015). "Although targeting SPOP in prostate cancer constitutes a considerable challenge, inhibiting downstream proteins escaping ubiquitination in SPOP mutant tumours may be more feasible, lending further credence to strategies targeting the P160 SRC family." (PMID 25896606, 2015). "To functionally characterize how SPOP mutations affect response to DSB, we expressed SPOP-wt and SPOP-F133V in benign prostate epithelial cells (RWPE) and prostate cancer cells (22Rv1), and examined the induction, recognition, and resolution of CPT-induced DSBs." (PMID 26374986, 2015). "To test if SPOP inactivation conferred sensitivity to PARP inhibition after DSB induction, we utilized siRNA targeting SPOP in human prostate cancer cell lines (PC-3, LnCap, 22Rv1), followed by irradiation (5GY) and incubation with the PARP inhibitors olaparib or veliparib." (PMID 26374986, 2015). "Because the majority of the AR variants identified thus far do not harbor the hinge domain, AR splicing represents a key mechanism by which the AR protein escapes SPOP-mediated polyubiquitination and proteasome degradation, thereby contributing to prostate cancer pathogenesis." (PMID 24508459, 2014).
prostate carcinoma (continued). "Our identification of SPOP as a bona fide E3 ligase of the AR is highly relevant to prostate cancer, because SPOP-mediated degradation of AR protein is disrupted by its mutations identified in prostate cancer, as well as the majority of prostate cancer-derived AR splicing variants." (PMID 24508459, 2014). "Here, we demonstrate that SPOP recognizes a Ser/Thr-rich degron in the hinge domain of androgen receptor (AR)and induces degradation of full-length AR and inhibition of AR-mediated gene transcription and prostate cancer cell growth." (PMID 24508459, 2014). "In this study, we identified AR as a degradation substrate of SPOP in prostate cancer cells." (PMID 24508459, 2014). "Notably, SPOP mutants derived from prostate cancer were found to cluster in their substrate-recruited MATH structural domains, thereby disrupting SPOP's ability to bind to and promote Nanog for polyubiquitination and degradation, ultimately suppressing the characterization of prostate CSCs." (PMID 40034124, 2025). "For example, mutations in the speckle-type POZ protein (SPOP), a substrate recognition component of the E3 ubiquitin ligase, can disrupt normal AR ubiquitination, leading to increased AR protein stability and enhanced AR signaling, ultimately increasing resistance in prostate cancer cells." (PMID 41079787, 2025). "Taken together, our findings elucidate a critical KMT2D/G3BP1/SPOP/AR regulatory axis in prostate cancer progression and propose that targeted inhibition of histone methylation in combination with anti-androgen therapy represents a promising strategy for the management of advanced prostate cancer." (PMID 41247636, 2025). "However, it is important to note that SPOP mutation status does not necessarily correlate with the expression of SPOP mRNA in prostate cancer tissue." (PMID 40432836, 2025). "However, caution should be taken when pharmacologically inhibiting CHD1 in prostate cancer with SPOP or MAP3K7 deletions, reasoning that CHD1 inhibition may play tumor-promoting roles in these contexts." (PMID 36776288, 2023). "Both SPOP mutation and CDC20 overexpression are important in docetaxel resistance with the inhibition or knockdown of CDC20 being able to resensitise cells to docetaxel highlighting the importance of CDC20 as a therapeutic target in prostate cancer at several disease stages." (PMID 37509260, 2023). "In addition, the overexpression of serine peptidase inhibitor, Kazal type 1 (SPINK1), protein, although not defining a molecular subtype, has been reported in approximately 10% of primary prostate cancer and is both mutually exclusive from ETS rearrangements and associated with SPOP mutations." (PMID 35050902, 2022). "Besides, SPOP-mutant prostate cancers often accumulate BET proteins, including BRD2, BRD3 and BRD4." (PMID 36357379, 2022). "In addition, SPOP might regulate androgen (AR) signaling way and SPOP down-expression led to the activation of AR signaling exerting oncogenic effect in prostate cancer." (PMID 34838022, 2021). "Importantly, we further observed that depletion of SPOP with different sgRNAs could significantly elevate endogenous PDK1 protein levels, as well as well-established SPOP substrate Trim24 in prostate cancer cell lines." (PMID 34353330, 2021). "Thus, our studies suggest that SPOP would like to play dual functions to modulate AKT kinase activity either by targeting PTEN to activate AKT in ccRCCs or by targeting PDK1 to repress AKT in prostate cancer." (PMID 34353330, 2021). "Moreover, both in SPOP knockout prostate cancer cells and MEFs, SPOP depletion could enhance PDK1 protein levels coupled with increased AKT phosphorylation in T308." (PMID 34353330, 2021).